INS (insulin)
Diseases named in the same sentence as INS in open-access papers (continued):
Sharing a sentence is not in itself a finding about the gene and the disease.
type 1 diabetes (continued). "A small trial in individuals with type 1 diabetes and gastroparesis found that hybrid closed loop insulin pump therapy improved the mean percentage time that blood glucose was in range (3.9–10 mmol/l) from 26% to 58.4%, however neither gastrointestinal symptoms nor gastric emptying were evaluated." (PMID 36194250, 2022). "Patients diagnosed with type 1 diabetes at age 20-29 years were nearly 3-fold more likely to use an insulin pump, 5.2-fold for patients diagnosed at age 10-19 years, and about 10-fold for patients diagnosed at age <10 years, as compared with those diagnosed at ≥30 years." (PMID 35757419, 2022). "However, DTS can also prevent children from playing or participating in certain sports: Children using the artificial pancreas system for their type 1 diabetes have reported difficulties when playing sports due to the tendency of the insulin pump to fall." (PMID 36315239, 2022). "The initial studies of closed loop insulin delivery (where basal insulin levels are automatically adjusted to bring glucose levels within a target range) were studied in small numbers of women with type 1 diabetes over very short periods of time." (PMID 36714590, 2022). "This study aims to evaluate whether the use of automated closed-loop insulin delivery improves antenatal glucose levels in pregnant women with type 1 diabetes." (PMID 35382796, 2022). "The proposed device could potentially be used in a broad range of applications, such as an insulin dosing system for Type 1 diabetic patients, artificial organs to transport blood, organ-on-chip applications, and so on." (PMID 35630190, 2022). "The addition of the glucagon-like peptide 1 (GLP-1) receptor agonists or of a sodium–glucose cotransporter 2 (SGLT2) inhibitor to insulin therapy was shown to trigger small reductions in HbA1c compared with insulin alone in people with type 1 diabetes and also reduced body weight." (PMID 35721726, 2022). "Clinical and lifestyle characteristics of people with type 1 diabetes by insulin regimen." (PMID 35757419, 2022). "There is a dual shift in lower insulin secretion and heightened insulin clearance for at least 12-44 hours after exercise, the effect of which is observed in both healthy persons and individuals with insulin-dependent diabetes." (PMID 36147573, 2022). "It was demonstrated, almost 90 years ago, that many diabetic patients were “insulin insensitive”, and it was suggested that patients should be classified as insulin sensitive (later classified as Type 1 DM) and insulin insensitive or non-insulin-dependent diabetes (classified as Type 2 DM)." (PMID 36290725, 2022). "The aim of the current study was to investigate the application of and barriers to insulin pump therapy among patients with type 1 diabetes in China, which may contribute to better understanding the existing gap of treatment selection." (PMID 35757419, 2022). "We conducted a phase I-IIa, randomized, monocentric, double-blind, placebo-controlled clinical trial to evaluate the safety and impact of the combination treatment of Itolizumab and insulin on preserving beta cell function in adults with recent-onset type 1 diabetes." (PMID 35407396, 2022). "We present a 51-year-old woman with type 1 diabetes of 16 years duration, on insulin pump therapy for more than 10 years, who presented for follow-up 7 weeks after transitioning to a hybrid closed-loop insulin pump system with continuous glucose monitoring (CGM)." (PMID 36180933, 2022). "There’s something called Sugar Buddies that if somebody was type 1 diabetes can be paired with somebody who had type 1 diabetes for 20 years, and really very well insulin management, so we pair them with somebody who we know that he’s been really very well educated, managing." (PMID 36252133, 2022). "The recommended treatment method for type 1 diabetes is intensive insulin therapy." (PMID 35429987, 2022).
type 1 diabetes (continued). "Therefore, due to regular complications, the anticipated rise in the number of diabetic patients, and the rising costs of insulin, there is a drastic need for a change in approach and alternative treatments for type 1 diabetes." (PMID 35324794, 2022). "Therefore, there is a need for new adjunctive drugs to insulin treatment that would help manage excessive body weight in patients with type 1 diabetes." (PMID 35784568, 2022). "Patients diagnosed with type I diabetes are injected with insulin for the rest of their lives." (PMID 35705561, 2022). "D and insulin influenced bone regeneration in mice with type 1 diabetes." (PMID 36295498, 2022). "There are two types of DM: type I, known as “insulin independent diabetes”, which results from the body's inability to produce and secrete insulin and type II, known as “non-insulin-dependent diabetes”, which results from the inability of the cells to respond to the insulin produced by the body." (PMID 36573132, 2022). "The mechanisms responsible for the dyslipidaemia in type 1 diabetes remain unclear, but the subcutaneous route of insulin administration, that is responsible for peripheral hyperinsulinemia, may play a role." (PMID 35201418, 2022). "They demonstrated that MSC and CD34+ HSC transplantation were the most successful and effective approaches in patients with insulin-dependent diabetes as they resulted in occurrence of insulin-free period in 20–60% of the patients and 7–50% reduction in their insulin requirement." (PMID 35501872, 2022). "Carbohydrate counting and insulin management are mainly targeted to enable people with type 1 diabetes to self-manage the disease; furthermore, education about how to use fat and protein content to determine insulin dosing is recommended to improve glycemic control." (PMID 35459205, 2022). "Type 1 diabetes affects between 5 and 10% of patients and is characterized by a lack of insulin production and a higher variability in blood sugars, which requires exogenous insulin and more regular monitoring of blood glucose." (PMID 35646863, 2022). "Transplanting encapsulated insulin-producing cells may achieve a functional cure for type 1 diabetes, but efficacy is constrained by mass transfer limits." (PMID 36229614, 2022). "Both insulin glargine and insulin detemir have been revealed to be highly endured in children and youngsters with type-I diabetes and facilitate efficient control of glycemia accompanied by a remarkable decline in increasing blood glucose, yet not A1c extent, as opposed to NPH insulin." (PMID 35723344, 2022). "Since type 1 diabetes is caused by a lack of insulin production and secretion, insulin administration is the crux of treatment." (PMID 36671612, 2022). "The patient with hemophilia was managed with regular low-dose recombinant factor VIII replacement therapy, and the patient with type I diabetes mellitus was administered continuous insulin infusion and sliding-scale insulin therapy; both patients had an uneventful course." (PMID 35384491, 2022). "CANPs thus are one of the promising tactics to deliver insulin to treat type 1 diabetes patients." (PMID 35384787, 2022). "Patients with a lack of endogenous insulin (certain insulin-dependent T2D or type 1 diabetes) are at increased risk of DKA, with a higher incidence observed in patients with type 1 diabetes." (PMID 36294370, 2022). "The distinguishing pathophysiological feature of type 1 diabetes is the acute reduction or absence of insulin secretion due to the loss of pancreatic islet ß-cells." (PMID 36035393, 2022). "Most relevant for type 1 diabetes is insulin, one of a key antigens driving beta cell autoimmunity." (PMID 35464420, 2022). "We hypothesized that using closed-loop compared to standard insulin delivery would assist pregnant women with type 1 diabetes to achieve target antenatal glucose levels (TIR 3.5-7.8 mmol/L)." (PMID 35382796, 2022).
type 1 diabetes (continued). "However, optimal glycemic control in many individuals with type 1 diabetes is limited by hypoglycemia and the high burden of self-management required with frequent monitoring of blood glucose and adjustment of insulin dosing." (PMID 35733769, 2022). "In older patients with type 1 diabetes, insulin therapy is necessary." (PMID 36249753, 2022). "For example, the systemic injection of leptin in a non-obese rodent model of insulin-deficient type 1 diabetes, results in normalization of glycemia following a glucose challenge." (PMID 35454388, 2022). "In addition, in the study, we also investigated a group of type 1 diabetic patients, and found increased BCAA levels that were associated with lower C-peptide (i.e., lower insulin secretion)." (PMID 36187117, 2022). "In many such patients, diazoxide is ineffective, resulting in the need for a trial of SRL to reduce excess insulin secretion, before resorting to irreversible sub-total pancreatectomy with consequent development of insulin dependent diabetes and exocrine pancreatic insufficiency." (PMID 36237195, 2022). "It seems that 8 weeks of NMES has beneficial effects on the reduction of FBS and TDD of insulin therefore, it could be suggested as the contributory treatment in management of children and adolescents with type-1 diabetes." (PMID 36221091, 2022). "Generally, people with type 1 diabetes are advised to halve their usual bolus insulin dose after exercise, but after an endurance event of this duration then a greater reduction may be required." (PMID 36425473, 2022). "One could therefore wonder whether the Pax4-mediated conversion of somatostatin-producing cells into insulin-expressing cells could also occur in the gastrointestinal tract, an information of great importance for type 1 diabetes research." (PMID 35573999, 2022). "A 25-year-old man with type 1 diabetes on an insulin pump and continuous glucose monitoring on optimal blood glucose control (HbA1c 6.5%, 48 mmol/mol; glucose time-in-range 70-180 mg/dl, TIR, 90%; coefficient of variation, CV, 36%) switched to a fruitarian diet because of ideological beliefs." (PMID 35273984, 2022). "Studies found that patients’ satisfaction and quality of life are enhanced by utilizing insulin pumps based on increased freedom, flexibility in nutrition, and physical activity, even if managing type 1 diabetes is highly difficult and complex, even for adults." (PMID 36422210, 2022). "To date, insulin therapy is still the standard treatment for type 1 diabetes." (PMID 35242127, 2022). "For all patients having type I diabetes mellitus, insulin is the first-line treatment." (PMID 36381916, 2022). "Despite including insulin in the National List of Essential Medicines, the most common cause of death in type 1 diabetes in India is lack of access to insulin." (PMID 36237970, 2022). "Type 1 diabetes, previously known as insulin-dependent diabetes, is an autoimmune disorder that occurs due to the destruction of the pancreatic beta cells leading to significantly reduced secretion of insulin." (PMID 35807526, 2022). "A report shows that the patients with type 1 diabetes in China are facing stigma, fear, and guilt may discourage insulin pump use and multiple daily injections, especially for those who require pre-meal insulin injections at school." (PMID 36568429, 2022). "Furthermore, there is some experimental evidence from animal models and humans (mainly those with type 1 diabetes) that autonomic dysfunction contributes to impaired counterregulatory responses to insulin-induced hypoglycemia and to HAAF." (PMID 36318703, 2022). "Consistently, quercetin, which is metabolized in isorhamnetin, could reduce glucose levels by ameliorating insulin secretion in the streptozotocin-induced type 1 diabetes model in rats." (PMID 35054888, 2022). "Type 1 diabetes patients must rely on regular injections of manufactured insulin to survive." (PMID 35638288, 2022).
type 1 diabetes (continued). "When cells were exposed to pro-inflammatory cytokines (in vitro type 1 diabetes), trained serum preserved both insulin secretion and GCK expression, reduced expression of proteins related to apoptotic pathways, and also protected cells from cytokine-induced apoptosis." (PMID 36012692, 2022). "This feature is of great interest in the context of type 1 diabetes as reprogramming/engineering the gastrointestinal epithelium to generate insulin+ cells could allow for their continued replenishment despite a putative autoimmune attack." (PMID 35573999, 2022). "The DBLG1 (Diabeloop, Grenoble, France) has received the CE mark in Europe for use in adults with type 1 diabetes, while the Omnipod Horizon (Insulet, Billerica, Massachusetts, USA) and insulin-only iLet (Beta Bionics, Boston, Massachusetts, USA) are currently undergoing clinical trials." (PMID 35733769, 2022). "This is a Type I diabetes that requires insulin therapy for survival." (PMID 36290725, 2022). "Type I diabetes mellitus and latent autoimmune diabetes of the adults are forms of autoimmune diabetes mellitus that occur after destruction of the pancreatic β-cells, which leads to insulin depletion." (PMID 35918735, 2022). "As for type 1 diabetes, this may have been due to the need for glycemic level monitoring and insulin administration, which require close supervision." (PMID 36361022, 2022). "Closed-loop artificial pancreas; Glucose sensor; Insulin; Type 1 diabetes." (PMID 36411933, 2022). "Demographic characteristics of people with type 1 diabetes by insulin regimen." (PMID 35757419, 2022). "Although the STZ injection has been used to model insulin-deficient type 1 diabetes since the sixties, it does not completely mirror the human type 1 diabetic situation." (PMID 35327418, 2022). "Insulin is given to treat type 1 diabetes and control blood glucose levels." (PMID 35887304, 2022). "Diabetes type 1 (T1D) is an autoimmune disease characterized by immune-mediated pancreatic beta-cell destruction, resulting in the limitation of the abnormal production and secretion of insulin." (PMID 36439560, 2022). "Type 1 diabetes is an autoimmune disease characterized by insulin-producing β cell destruction." (PMID 35015736, 2022). "In the CGM TIME trial, which involved 144 children with type 1 diabetes for at least 1 year, patients were treated using a sensor‐augmented personal insulin pump with the LGS function, and parents completed the HFS‐II questionnaire at baseline and after 12 months of treatment." (PMID 35620854, 2022). "These improvements include technological advancements in insulin delivery, marked advances in glucose monitoring and the recognition that these technical advances need to be accompanied by personal and psychosocial support for people with type 1 diabetes." (PMID 35994083, 2022). "Adherence to insulin therapeutic regimens in patients With type 1 diabetes." (PMID 35195219, 2022). "According to related studies in patients with insulin-dependent diabetes, the incidence of hypoglycemic attacks in patients taking regular insulin is higher than that in patients taking newer insulins, including lispro, which is consistent with our reported case." (PMID 35858952, 2022). "Alternatively, these reduced insulin responses could represent recurrence of autoimmune beta cell damage similarly to that observed with reduced first phase insulin responses in pre-type 1 diabetes patients." (PMID 34335462, 2021). "Type 1 diabetes (T1D) is an organ-specific autoimmune disease characterized by severe autoimmune destruction of insulin-secreting pancreatic beta cells, especially by the combined actions of different immune cells, such as CD4 and CD8 conventional T cells with specificity for islet autoantigens." (PMID 34054801, 2021). "As the use of insulin pumps increasingly becomes a standard of care in type 1 diabetes management, a fortuitous opportunity for improving sleep may be possible." (PMID 33628834, 2021).
type 1 diabetes (continued). "Elevated expressions of kininogen-1 respectively prekallikrein (cleaves kininogen to vasoactive peptide bradykinin) have also previously been described in type 1 diabetic patients and rats, which in rats further could be reversed with insulin treatment." (PMID 34580391, 2021). "We found differences in insulin concentrations according to several factors, but the values remained within the normal ranges, indicating no profound impairment in insulin production or secretion, as found in type 1 diabetes." (PMID 33740034, 2021). "People with type 1 diabetes and hospitalization for hypoglycaemia appeared to receive similar insulin treatment regimens as the type 1 diabetes comparisons, with similar dynamic tendencies in insulin therapy preceding and after the event date." (PMID 34277957, 2021). "In addition to prolonging the life expectancy of people living with type 1 diabetes, the discovery of insulin a century ago revolutionised the management of this chronic autoimmune disease." (PMID 33595677, 2021). "Interestingly, analysis of pancreatic sections representing individuals with type 1 diabetes showed persistence of heterodimer expression beyond that of insulin, potentially enabling identification of beta cell remnants." (PMID 33859325, 2021). "On the other hand, type 1 diabetes (T1D) is an autoimmune disease characterized by the destruction of insulin-producing beta cells of the pancreatic islets of Langerhans, producing chronic inflammation and a progressively severe insulin deficit." (PMID 33672659, 2021). "Type 1 diabetes is the autoimmune destruction of the insulin producing beta-cells." (PMID 34805976, 2021). "Healthy glycemic controls need to be preserved in type 1 diabetes, requiring at least three or maybe more daily insulin shots." (PMID 33466845, 2021). "As well as being a negative regulator of insulin secretion, ghrelin also seems to have protective effects on the β-cells despite evidence showing that levels of ghrelin decline with the onset of type 1 diabetes." (PMID 34294136, 2021). "Normalized insulin remains the mainstay for treating type 1 diabetes (T1D)." (PMID 33494161, 2021). "The treatment options for type 1 diabetes are limited to insulin replacement therapy." (PMID 34882233, 2021). "Taken together, the authors suggest a potential benefit to adding GLP-1 to insulin therapy in adults with type 1 diabetes and offer different mechanisms by which GLP-1 may mediate these improvements." (PMID 33828529, 2021). "However, although less than a half of the population of people with type 1 diabetes in these regions use insulin pumps, the uptake of insulin pumps is much higher among children and adolescents." (PMID 33571104, 2021). "Thus, people with type 1 diabetes depend on multiple daily insulin injections and on managing multiple self-care tasks to maintain a glucose level close to the normal range." (PMID 33413645, 2021). "Insulin therapy has a significant role in treating type 1 diabetes." (PMID 33466845, 2021). "Selection elimination of anti-insulin B cells prevents disease in type 1 diabetes-prone mice; targeting ASBCs may thus offer an effective alternative to broad immunosuppression for autoimmune disease prevention and treatment." (PMID 34234784, 2021). "In 2021, a full century has passed since the 1921 discovery of insulin, a hormone that must be replaced in individuals with type 1 diabetes (T1D), all of whom have lost the ability to produce it as the result of primarily autoimmune destruction of the pancreatic β-cells." (PMID 34501920, 2021). "This was probably due to insulin treatment in young people with type 1 diabetes." (PMID 33672913, 2021). "Type 1 diabetes mellitus (T1DM) is a metabolic disease characterized by the autoimmune-mediated destruction of the pancreatic β-cells that leads to a deficit in the production of insulin with various repercussions on the intermediary metabolism." (PMID 34199272, 2021).